PTF1A (pancreas associated transcription factor 1a)
Diseases named in the same sentence as PTF1A in open-access papers (continued):
Sharing a sentence is not in itself a finding about the gene and the disease.
diabetes (15 papers, 2007 to 2026). "In this report, NPH insulin was selected as the initial treatment for diabetes resulting from a PTF1A enhancer mutation, following established neonatal diabetes protocols." (PMID 40443916, 2025). "Regular follow-up allowed for continuous insulin adjustments as the patient's needs evolved, particularly given the long-term nature of diabetes associated with PTF1A mutations." (PMID 40443916, 2025). "A homozygous variant within the distal enhancer of the PTF1A gene was identified in one female proband who presented with diabetes, hepatomegaly, liver derangement, anemia, malabsorption, and multiple skeletal dysplasia." (PMID 40302952, 2024). "All participants who were positive for pathogenic PTF1A enhancer variants were diagnosed earlier than other children with neonatal diabetes, at 12–35 days of age." (PMID 37897565, 2023). "Here, we present six cases of pancreatic agenesis resulting in neonatal diabetes with PTF1A gene mutation." (PMID 37854477, 2023). "In this large series of patients with PTF1A distal enhancer mutations, we highlight the importance of genetic testing and clinical follow-up studies to characterize rare genetic subtypes of diabetes." (PMID 32893856, 2020). "We have evaluated the presenting clinical characteristics, molecular genetics, and long-term follow-up of the largest series to date of patients with diabetes and pancreatic agenesis due to PTF1A distal enhancer mutations." (PMID 32893856, 2020). "Out of the 80 DE-genes, three genes Clcnka (downregulated) and Ptf1a and Pik3c2a (both up-regulated) are shared with the diabetes-associated genes list." (PMID 29995913, 2018). "Ablation of either Pdx1 or Ptf1a causes pancreatic agenesis or diabetes and wide gastro-duodenal deformations." (PMID 30425728, 2018). "Regarding the age of onset of diabetes, previous reports of patients with PTF1A truncating mutations showed that they had diabetes in the first month of life." (PMID 28663161, 2017). "The three patients with mutations in distal enhancer region of PTF1A presented with diabetes at a median age of 3 weeks (range 1–10 weeks)." (PMID 25755231, 2015). "Past work has identified Ptf1a as the responsible gene for permanent neonatal diabetes mellitus associated with pancreatic and cerebellar agenesis." (PMID 17910758, 2007). "We report the largest series of patients with diabetes caused by PTF1A enhancer mutations." (PMID 32893856, 2020). "This is in keeping with previously published cases with the Chr10:g.23508437A>G PTF1A enhancer mutation, for whom intrafamilial variability was observed with some individuals developing diabetes outside the neonatal period and having subclinical exocrine pancreas insufficiency." (PMID 32893856, 2020). "Since all the previously reported cases with a delayed diagnosis of diabetes had the Chr10:g.23508437A>G PTF1A distal enhancer mutation, it is possible that this variant does not entirely abolish the enhancer activity and causes pancreas hypoplasia with some residual beta-cell mass." (PMID 32893856, 2020). "Thirty patients with diabetes caused by PTF1A enhancer mutations." (PMID 32893856, 2020). "However, patients with PTF1A enhancer mutations had phenotypic variability: The majority of cases are diagnosed in the first month of life, but diabetes at later ages was also observed." (PMID 28663161, 2017). "At this stage, progenitor cells typically co-express PDX1, NKX6.1, and PTF1A, failure of endocrine cell formation leads to diabetes in mice." (PMID 30425728, 2018). "In permanent neonatal diabetes (PNDM) patients, homozygous GCK (n=6), EIF2AK3 (n=3), PTF1A (n=3), and INS (n=1) and heterozygous KCNJ11 (n=2) mutations were identified." (PMID 25755231, 2015). "A rare coding hypomorphic mutation in the PTF1A gene was reported in four individuals from two different families who had the same novel mutation, p.P191T, and presented with permanent neonatal diabetes (PNDM) without cerebellar manifestations." (PMID 37854477, 2023).
diabetes (continued). "In addition to NKX6–1 we found variants in WFS1, RFX6 and 7 other genes associated with monogenic forms of diabetes (AKT2, EIF2AK3, GLIS3, HADH, MNX1, NKX2–2, and PTF1A) and they may be relevant to development of MODY." (PMID 29439679, 2018). "Lin-/VEGF-R2+ D-EPCs showed upregulation of Ptf1a that may be a compensatory action in diabetes." (PMID 29995913, 2018). "The spectrum of causative genes (PTF1A, GLIS3, WFS1, INSR, SLC29A3, ZNF808, ABCC8, INS) is markedly different from the monogenic diabetes genes seen in non-consanguineous cohorts, and also different from those seen in other consanguineous populations." (PMID 37897565, 2023). "Five children (8%) had pathogenic variants that do not cause syndromic diabetes (GCK [n = 2], HNF1A [n = 1], INS [n = 1], and the PTF1A enhancer [n = 1]); thus, these additional features are likely to be coincidental and unrelated to the monogenic diabetes diagnosis." (PMID 40746173, 2026).
cerebellar agenesis (11 papers, 2010 to 2024). "Mutations in PTF1A, another gene associated with cerebellar agenesis, were also ruled out." (PMID 35162247, 2022).
pancreatitis (8 papers, 2015 to 2023). Inflammation of the pancreas. "Acinar-derived EYFP+ cells in caerulein-treated Ptf1a cKO pancreata were instead integrated within CK19+ duct-like structures, suggesting that pancreatitis synergizes with loss of Ptf1a to cause a rapid loss of acinar gene expression and complete reprogramming to a duct-like fate." (PMID 26151762, 2015). "Our findings suggest that PTF1A acts in a dosage-sensitive manner to safeguard the pancreatic acinar population against both oncogene activity and environmental insults, such as damage caused by pancreatitis." (PMID 26151762, 2015). "A failure to achieve complete acinar maturation is associated with more severe damage and delayed recovery during caerulein-mediated pancreatitis in several genetic mouse models including those where Gata6, Mist1, and Ptf1a are inactivated in the pancreas." (PMID 37353485, 2023). "Recent investigations have further shown that PTF1a is poorly expressed at the onset of pancreatitis, while one study remarked that deletion of PTF1a alone is enough to precipitate inflammatory response of pancreatic cells." (PMID 35725649, 2022). "These animals were then used to determine the role of Piezo1 in mediating pressure-induced pancreatitis by subjecting tamoxifen-treated Ptf1a-CreER;Piezo1fl/fl (Piezo1aci KO) and Piezo1fl/fl (WT) mice to intrapancreatic duct pressure." (PMID 29712913, 2018). "In these studies, Cre was activated with tamoxifen at 8 weeks, when Ptf1a-driven expression is restricted to acinar and centro-acinar cells, followed by caerulein-induced pancreatitis to accelerate transformation." (PMID 29170413, 2017). "In contrast, Ptf1a cKO mice subjected to caerulein-induced pancreatitis exhibited widespread acinar atrophy, persistent inflammation, fibrotic stroma, and the appearance of mucinous metaplastic structures." (PMID 26151762, 2015). "ADM cells showed a bivalent stage of H3K4me3 and H3K27me3 on the Ptf1a, Rbpj and Rbpjl promoter, which might explain their plasticity towards acinar cell redifferentiation in pancreatitis-driven regeneration or towards tumor cell dedifferentiation in the presence of oncogenic Kras." (PMID 26716510, 2016). "Consistently, forced expression of acinar cell-related TFs (Ptf1a or Mist1) successfully inhibits Kras-mediated activation of the ERK signaling pathway and ADM formation in a caerulein-induced pancreatitis model." (PMID 29802314, 2018). "Among the upstream mediators activated in the Ptf1a cKO model are TNF-α and NFkB, both of which promote ADM and inflammation in pancreatitis and amplify KRAS activity in pancreatic tumorigenesis." (PMID 26151762, 2015). "Nonetheless, Ptf1a cKO pancreata did not exhibit a general pancreatitis phenotype nor did they exhibit a detectable increase in epithelial cell apoptosis." (PMID 26151762, 2015).
pancreatic ductal adenocarcinoma (5 papers, 2015 to 2022). An infiltrating adenocarcinoma that arises from the epithelial cells of the pancreas. "PTF1A is one of the key regulators in pancreas organogenesis and murine Ptf1a-Cre lines are commonly used for the generation of pancreatic ductal adenocarcinomas (PDAC) mouse models." (PMID 34692545, 2021).
acute pancreatitis (3 papers, 2015 to 2017). An acute inflammatory process that leads to necrosis of the pancreatic parenchyma. "In order to investigate Rab7 participation in acute pancreatitis, we generated pancreas-specific Rab7-deficient (Rab7Δpan) mice by crossing Rab7flox/flox mice and Ptf1a-Cre mice." (PMID 28588238, 2017). "Taken together, these data demonstrate that PTF1A is necessary for acinar-cell redifferentiation and resolution of tissue injury following acute pancreatitis." (PMID 26151762, 2015). "In addition, our preliminary experimental results showed the emergence of Sox9/Ptf1a double positive cells in the tissue restoration after cerulein-induced acute pancreatitis." (PMID 25687338, 2015).
cerebellar ataxia (3 papers, 2010 to 2021). A neurological syndrome characterized by clumsy and uncoordinated movement of the limbs, trunk, and cranial muscles. "Based on its importance during pancreas development and cerebellar neurogenesis, mutations in PTF1A can cause cerebellar ataxia and permanent neonatal diabetes mellitus in humans." (PMID 34692545, 2021). "In humans, Ptf1a was identified as responsible for the human permanent neonatal diabetes mellitus associated with cerebellar ataxia, and was reported to be involved in cerebellar development." (PMID 23436999, 2013). "These motor performance deficits in the Ptf1a::cre;Robo3lox/lox mice were so severe that it appeared as if their ataxia was worse than that of mice that have no cerebellar output at all." (PMID 20231872, 2010).
Glucose intolerance (3 papers, 2016 to 2020). Glucose intolerance (GI) can be defined as dysglycemia that comprises both prediabetes and diabetes. "A similar phenotype was identified in a Ptf1a–/– mouse model, where the severity of pancreatic hypoplasia, pancreatic exocrine insufficiency, and glucose intolerance was shown to correlate with the Ptf1a mRNA levels, suggesting a dosage-dependent effect." (PMID 32893856, 2020). "Reduced Ptf1a levels leads to pancreatic hypoplasia and glucose intolerance." (PMID 33424774, 2020).
pancreatic exocrine insufficiency (3 papers, 2015 to 2020). "Here, we report a patient with neonatal diabetes and exocrine pancreas insufficiency resulting from compound heterozygous mutations in the PTF1A gene." (PMID 28663161, 2017).
chronic pancreatitis (2 papers, 2015 to 2023). A chronic inflammatory process causing damage and fibrosis of the pancreatic parenchyma. "Pancreatic histology in Ptf1a-CreERTM control mice were similar to those found in human chronic pancreatitis patients." (PMID 36835366, 2023). "These resemble tubular complexes observed in human and mouse chronic pancreatitis, suggesting that dysregulation of PTF1A expression or function might be involved in the etiology of this disease and its well-known contribution to PDAC risk." (PMID 26151762, 2015).
developmental delay (2 papers, 2018 to 2023). "Here we report three patients with neonatal diabetes; two with isolated pancreas agenesis due to mutations in the pancreas-specific transcription factor 1A (PTF1A) enhancer and one with developmental delay, epilepsy, and neonatal diabetes (DEND) syndrome, due to a KCNJ11 mutation." (PMID 28943513, 2018).
MODY (2 papers, 2018 to 2024). "Other rare variants found in a South Indian population that could potentially play a role in MODY pathogenesis are EIF2AK3, GLIS3, HADH, and PTF1A." (PMID 39201476, 2024).
pancreatic adenocarcinoma (2 papers, 2014 to 2021). "Compared with control Tg(ptf1a:eGFP), we observed a significant increase in apoptosis in pancreatic adenocarcinoma of Tg(ptf1a:Gal4;UAS:eGFP-KRASG12D) injected animals." (PMID 24878567, 2014). "Upon comparison of pancreatic adenocarcinoma with concomitant ptf1a-induced medulloblastoma in the cerebellum, they conclude that TGFβ, Shh and Notch are involved in both cancers at different stages of carcinogenesis." (PMID 24878567, 2014). "To generate a zebrafish model of pancreatic adenocarcinoma, eggs derived from Tg(ptf1a:Gal4) outcrosses were injected with Tol2(UAS:eGFP-KRASG12D) plasmid; we call these samples “Tg(ptf1a:Gal4)/UAS:eGFP-KRASG12D injected”." (PMID 24878567, 2014).
cyst (1 paper, 2015). A sac-like closed membranous structure that may be empty or contain fluid or amorphous material. "Neither control nor Ptf1a cKO acinar clusters underwent spontaneous cyst conversion, in the absence of added growth factors, implying that loss of Ptf1a is not sufficient for acinar-ductal reprogramming." (PMID 26151762, 2015).
glioma (1 paper, 2020). A benign or malignant brain and spinal cord tumor that arises from glial cells (astrocytes, oligodendrocytes, ependymal cells). "For instance, while the ptf1a (pancreas associated transcription factor 1a) promoter is active in cerebellum, hindbrain and pancreas, Tg(ptf1a:Gal4; UAS:KRASG12V) double-transgenics develop pancreatic tumors, whereas Tg(ptf1a:Gal4; UAS:AKT1Myr) present glioma." (PMID 32759814, 2020).
medulloblastoma (1 paper, 2014). A malignant, invasive embryonal neoplasm arising from the cerebellum. "As expected by eGFP-KRASG12D tissue-specific expression driven by ptf1a, we found the hallmark features of an undifferentiated medulloblastoma in both the external granular layer and ventricular zone in 5 out of 35 samples analyzed at 1 mpf." (PMID 24878567, 2014). "The selected ptf1a promoter also drives conditional KRASG12D expression in cerebellum; thus, we were able to assess KRAS activity during the early stages of cerebellar development by obtaining a concomitant model of putative pediatric medulloblastoma (MDB)." (PMID 24878567, 2014).
myeloid leukemia (1 paper, 2021). A clonal proliferation of myeloid cells and their precursors in the bone marrow, peripheral blood, and spleen. "Thus, it is possible that RBPJL offers a selective advantage for certain subtypes of myeloid leukemia, even in the absence of PTF1a, most probably deregulating Notch target genes." (PMID 34638511, 2021).
neuroendocrine tumor (1 paper, 2018). "PTF1A was expressed in all normal and neuroendocrine tumor cells." (PMID 29713473, 2018). "Unlike the NKX2.2, PDX-1, and CDX-2 that had restricted expression pattern in NETs of different site, PTF1A was expressed in all normal and neuroendocrine tumor cells (data not shown)." (PMID 29713473, 2018).
ovarian carcinoma (1 paper, 2021). A malignant neoplasm originating from the surface ovarian epithelium. "Furthermore, PTF1A is involved in the Notch-mediated HES/HEY network, which has been found by many studies being activated in ovarian cancer." (PMID 34149794, 2021).
type 2 diabetes (1 paper, 2023). "Genetic variants in or near the CDKAL1, KLF9, GP2, ALDH2, and ITIH4 genes are associated with obesity and genetic variants in or near the GDAP1, PTF1A, SIX3, ALDH2, and PAX4 genes are specifically associated with type 2 diabetes in East Asians." (PMID 37749090, 2023).
tumor (28 papers, 2014 to 2026). "Our findings, that the acinar specific complex PTF1 is epigenetically silenced in ADM and tumor cells corroborate existing studies showing that a loss of Ptf1a supports acinar reprogramming, which in turn makes the cells more susceptible towards oncogenic transformation." (PMID 26716510, 2016). "Ptf1a + /Cre-mediated Hes1 deletion caused defective exocrine differentiation with accumulation of acinar progenitors, which may contribute to the accelerated tumor development." (PMID 39548190, 2025). "Previous studies examined PTF1A binding in a mouse acinar tumor cell line or in mouse neural tube and later stages of pancreas organogenesis in which PTF1A is expressed in acinar cells." (PMID 35998583, 2022). "This strategy permitted an assessment of PTF1a's ability to sensitize an already established PDAC tumor." (PMID 29719936, 2018). "Analysis of control vs. +Dox groups revealed that inducing PTF1a expression in established tumors produced only minor and statistically insignificant decreases in tumor burden." (PMID 29719936, 2018). "As PTF1a expression resulted in increased sensitivity to gemcitabine, we next tested the ability of induced PTF1a to increase tumor sensitivity to gemcitabine in vivo." (PMID 29719936, 2018). "ADM cells showed a bivalent state with similar levels of H3K4me3 and H3K27me3, whereas tumor cells exhibited an enrichment of H3K27me3 at the Ptf1a and Rbpjl promoter and a slightly elevated H3K4me3 modification at the Rbpj promoter." (PMID 26716510, 2016). "In agreement with the gene expression data, we detected an enrichment of the repressive histone marks H2AK119ub and H3K27me3 at the Ptf1a and Rbpjl promoter in tumor cells." (PMID 26716510, 2016). "As above, KPC mice (Pdx1-Cre; KrasLSL-G12D; p53lox/+) were generated on either Ptf1a+/+ or Ptf1aΔ/+ backgrounds, and animals were monitored for tumor-free survival." (PMID 26151762, 2015). "Of note, Makoto and his colleagues showed that activated WNT signaling in the tumor stromal microenvironment contributes to the development of murine pancreatic MCNs in Ptf1a-Cre-LSL-Kras-elastase-tva mice injected with replication-competent-avian-sarcoma (RCAS)-WNT1 viruses." (PMID 33924999, 2021). "However, when established tumors were provided both Dox (to activate PTF1a) and gemcitabine, total tumor burden decreased by 55%, a 1.4‐fold enhancement in gemcitabine sensitivity." (PMID 29719936, 2018). "Identification of ‘cancer’ pathways suggested that tumor‐associated properties may be decreased when MIST1 and PTF1a are induced in PDAC cells." (PMID 29719936, 2018). "Thus, activating/inducing PTF1a in PDAC tumor cells may provide a new therapeutic venue to decrease PDAC progression by lowering CSC properties." (PMID 29719936, 2018). "Collectively, these data provide evidence that induced expression of PTF1a reduces pancreatic CSC properties and overall PDAC tumor growth in orthotopic assays." (PMID 29719936, 2018). "Moses’s laboratory generated TGF-βRII knock out mice crossed with Ptf1a-Cre; LSL-KrasG12D and showed that compound mice developed well differentiated PDAC mostly highlighting the role as a tumor suppressor." (PMID 30065235, 2018).